CD34 (CD34 molecule)
Diseases named in the same sentence as CD34 in open-access papers (continued):
Sharing a sentence is not in itself a finding about the gene and the disease.
ischemic disease (7 papers, 2012 to 2023). Lack of blood supply to an area of the body, resulting in impairment of tissue oxygenation. "Differing CD34+ EPCs responses might underlie increased risk of ischemic diseases associated with age." (PMID 29708992, 2018). "Prior to their use in ischemic disease, CD34+ stem cells were used in hematopoietic reconstitution after myeloablative therapy in many cancer patients." (PMID 34066713, 2021). "Recent studies suggested that transplantation of CD34+ stem cell-derived exosomes (CD34+-Exos) can treat ischemic diseases by promoting neovascularization and that miR-26a is an important positive regulator of osteogenesis." (PMID 31730486, 2019). "Studies have reported that intramuscular injection of autologous CD34+ stem cells can increase angiogenic activity and myogenesis in critical limb ischemia and decrease the amputation rate, which is promising for the treatment of ischemic disease." (PMID 31730486, 2019). "However, stem cell transplantation still has many defects, such as the low survival rate, genetic variation, and tumorigenesis, which limit the application of CD34+ stem cells in ischemic disease." (PMID 31730486, 2019). "Noteworthy, the administration of purified CD34+/KDR+ progenitor cells promoted vascular regeneration in ischemic limbs of mice and might therefore provide an interesting tool for therapeutic angiogenesis in ischemic diseases." (PMID 22506045, 2012).
liver cirrhosis (7 papers, 2014 to 2023). "CD34-PAS staining implicated that poorly vascularized micro-HCCs growing on liver cirrhosis tended to respond better to CA4P treatment." (PMID 28903414, 2017). "G-CSF can promote CD34+ hematopoietic stem cell mobilization through regulation of stem cells mobilization-related factors in patients with liver cirrhosis and HBV-associated acute-on-chronic hepatic failure." (PMID 24976843, 2014). "This study demonstrated a close relationship between endoglin and liver cirrhosis, in contrast to CD34 antibody, which is a good endothelial marker of hepatic carcinogenesis." (PMID 24507660, 2014). "This study identified a close relationship between CD105 and liver cirrhosis, and that CD34 antibody is a good endothelial marker for hepatic carcinogenesis." (PMID 24507660, 2014). "None of the multiple biomarkers included in the analyses (age, tumor number, intratumoral lymphocytes, liver cirrhosis, Hep Par 1, CD34, Glypican 3) reached statistical significance (p = 0.68, p = 0.22, p = 0.54, p = 0.60, p = 0.68, p = 0.79, and p = 0.53, respectively)." (PMID 37174934, 2023). "Interestingly, a recent study has treated patients with decompensated liver cirrhosis with autologous GM-CSF-mobilized peripheral blood CD34+ cells obtained after apheresis." (PMID 30071043, 2018).
myofibroblastoma (7 papers, 2013 to 2024). A benign, well circumscribed soft tissue neoplasm characterized by the presence of spindle shaped myofibroblasts and mast cells in a collagenous stroma. "The combination of ER, CD34, SMA, and desmin expression and loss of Rb expression is characteristic of myofibroblastoma." (PMID 34322734, 2022). "The sensitivity of CD34 and desmin for detecting mammary-type myofibroblastoma is close to 90%." (PMID 30567070, 2018). "CD34 staining can be used to differentiate myofibroblastoma from desmoid fibromatosis, as it is almost always negative in the latter." (PMID 39526189, 2024). "Intranodal schwannoma were often positive for vimentin and S100, which are similar with myofibroblastomas, and negative for SMA and CD34, which are not similar with myofibroblastomas." (PMID 26911514, 2016).
portal hypertension (7 papers, 2009 to 2025). Increased blood pressure in the portal venous system. "The results of anti-CD34 staining in this case suggest the presence of portal hypertension, which is consistent with the patient's clinical manifestation." (PMID 38388441, 2024). "In two instances from different families, CD34 stained positive in sinusoidal endothelial cells, consistent with portal hypertension." (PMID 19936245, 2009). "The expression of CD34 in sinusoidal endothelial cells was detected in two TERT mutation patients with non-cirrhotic portal hypertension, indicating an abnormal proportion of arterial blood flow to the sinuses." (PMID 39849589, 2025). "In summary, our data suggest that G-CSF-mobilized CD34+ HSCs, given their potential to engraft into liver tissue and their ability to ameliorate the injurious effects of radiation, might provide a new approach for the treatment of some liver diseases." (PMID 20633298, 2010). "In this study, to investigate the mechanism of liver diseases induced by HIV infection and ART, we used NRG mice reconstituted with human fetal liver–derived CD34+ progenitor cells to model HIV-induced liver disease with stable ART as reported in PLWH." (PMID 35639478, 2022).
refractory anemia (7 papers, 2008 to 2024). "In addition, we observed a significant increase in the expression of the phosphatases PTEN, INPP4B, and SHIP1 in MDS CD34+ cells compared to healthy CD34+ cells, particularly in the refractory anemia (RA) with excess blasts (RAEB) subset of high-risk MDS cases." (PMID 36812307, 2023). "Apoptosis is one of the most notably activated pathways in CD34+ cells from refractory anemia (RA) patients, when compared to healthy controls or refractory anemia with excess blast (RAEB) patients." (PMID 36428749, 2022). "Expression of FBXL5 was significantly downregulated in the CD34+ cells of patients with refractory anaemia with ringed sideroblasts (RARS), a subgroup of MDS characterized by iron deposition and apoptosis in hematopoietic progenitor cells." (PMID 28714470, 2017). "Additionally, we observed that patients with refractory anemia with excess blasts (RAEB)‐type MDSs who had lower levels of ABIN1 expression in their CD34+ cells had poorer survival rates." (PMID 38009796, 2024).
renal carcinoma (7 papers, 2009 to 2025). A carcinoma arising from the epithelium of the renal parenchyma or the renal pelvis. "In vivo analyses demonstrated that renal cancer exosomes promoted tumor metastasis, and CD34-positive cell rate in tumor foci significantly increased." (PMID 34179017, 2021). "Macrophages generated from CD34+ progenitors by cytokines produced from a renal carcinoma cell line were also shown to be defective in APC function, although they exerted powerful phagocytic activity and expressed the same surface phenotype markers with peripheral blood macrophages." (PMID 20107535, 2009). "One explanation for this paradoxical difference between the two renal cancer types is that KIRP has a rich papillary architecture while KIRC is comparatively more vascular as shown by the higher expression of vascular marker genes (CD34 and CD31) in KIRC compared to KIRP (p-values < 2.2 e−16)." (PMID 40615649, 2025). "ELTD1, CD34 and VEGF receptor 2 (VEGFR2) expressions were analysed in tumor vessels of renal cancer tissues from 139 patients with mRCC using immunohistochemistry." (PMID 32321460, 2020). "We have also found that MYBBP1A knock down increases the expression of CD34, NANOG and CXCR4, which are target genes of c-MYB, exclusively in renal carcinoma cell lines that express high levels of c-MYB." (PMID 30781655, 2019).
spindle cell sarcoma (7 papers, 2021 to 2026). A malignant mesenchymal neoplasm composed of spindle-shaped cells. "Histopathological analysis of the metastatic lesion revealed spindle cell sarcoma with decreased GPC-3/Hepa expression and elevated CD34/Ki-67 expression." (PMID 41908529, 2026). "Postoperative pathological results confirmed the renal vein leiomyosarcoma: spindle cell sarcoma, diffuse severe atypia, S-100 (-), SMA ( +), desmin ( +), CD34 (−), CD99 ( +)." (PMID 35761392, 2022). "Pathology revealed spindle cell sarcoma, diffuse severe atypia, S-100 (−), SMA (+), desmin (+), CD34 (−), CD99 (+)." (PMID 35761392, 2022). "After extensive immunohistochemical analysis, including antibodies against pan-cytokeratin, S100, CD34, beta-catenin, SMA, desmin, CD10 and MDM2, the tumor was classified as high-grade spindle cell sarcoma NOS." (PMID 35645621, 2022). "Immunohistochemical staining showed positive immunoreactivity for vimentin and negative for desmin, SMA and CD34 antibodies that are useful to distinguish this type of cancer from other spindle cell sarcomas." (PMID 40788189, 2025). "Nevertheless, expression has been observed in other types of tumours; CD34 expression can be detected in other fibroblastic and myofibroblastic tumours but is lost in aggressive SFTs, whereas BCL-2 is expressed in other fibroblastic spindle cell sarcomas." (PMID 40933515, 2025). "The lung case presented as a low-grade spindle cell sarcoma composed of monomorphic spindle cells arranged in a pattern-less pattern, partly reminiscent of SFT with prominent stromal and perivascular hyalinization and co-expression of S100 and CD34." (PMID 32860002, 2021).
angioleiomyoma (6 papers, 2013 to 2025). A benign, slow-growing neoplasm that arises from the dermis or subcutaneous tissue. "Surgical excision followed by histopathological and immunohistochemical (IHC) analysis established the diagnosis of angioleiomyoma, marked by desmin-positive smooth muscle fibers and CD34-positive vasculature." (PMID 40755624, 2025).
Autoimmunity (6 papers, 2009 to 2025). The occurrence of an immune reaction against the organism's own cells or tissues. "Our model used mice reconstituted with CD34+ HSCs cells derived from donors with HLA alleles predisposed to autoimmune disorders." (PMID 36936963, 2023). "In contrast to autoimmunity, CD34+‐humanized mice are a valuable tool for immuno‐oncology (IO) research." (PMID 40591148, 2025). "Another avenue for studying autoimmunity in humanized mouse models is to inject or vaccinate CD34+‐reconstituted mice with chemicals or compounds capable of initiating inflammatory responses that lead to autoimmune syndromes." (PMID 40591148, 2025). "CD34+ selection, on the one hand, theoretically improves the results of AHSCT and, on the other hand, increases the risk of secondary autoimmunity." (PMID 34181099, 2021). "Thus, the presence of TLS in CD34+‐humanized mouse models of autoimmunity is still a matter of debate and should be analyzed more systematically." (PMID 40591148, 2025). "V(D)J recombination is a defining characteristic of adaptive immunity, and as a result the findings reported here underscore the profound effect of myeloablative conditioning and CD34-selected autologous stem cell transplant on subsequent host adaptive immunity and autoimmunity." (PMID 36241361, 2023). "Finally, NKG2D, a powerful activating receptor involved in the regulation of immune responses during infection, cancer and autoimmunity, was preferentially detected on CD34-lineage- cells cultured with IL-15 and IL-21." (PMID 19712464, 2009).
Burkitt lymphoma (6 papers, 2013 to 2024). A rare form of malignant mature B-cell non-Hodgkin lymphoma. "A 27-year-old male with HIV-associated naïve and high-risk Burkitt’s lymphoma sequentially received short-term, high-dose non-myeloablative chemotherapy and autologous CD34-positive stem cell transfusion in the setting of combined antiretroviral therapy (cART)." (PMID 30572947, 2018). "Immunohistochemical and molecular studies demonstrated typical features of sporadic Burkitt lymphoma: the atypical cells were positive for CD20, CD79a, CD10, CD23, HLA-DR, bcl-6, PAX5, c-myc, and cytoplasmic IgM, but negative for CD3, CD5, CD15, CD30, CD34, TdT, bcl-2, and MUM1." (PMID 34868769, 2021). "IG::MYC: Although IG::MYC translocations are typical of Burkitt lymphoma (BL), WHO-HAEM5 reports infrequent cases of BL with a phenotype of precursor B-cells including expression of terminal deoxynucleotidyl transferase, sometimes CD34, and absence of CD20 and surface immunoglobulin expression." (PMID 38835965, 2024).
cerebrovascular diseases (6 papers, 2013 to 2025). "Again, similar to the proportion (%), the concentration of CD34+CD133+ EPCs per mL was found to have similar associations with AD dementia in the presence of peripheral or cerebrovascular diseases." (PMID 38854406, 2024). "Pilot and randomized clinical trials demonstrated the safety, feasibility, and effectiveness of the CD34+ cell therapy in peripheral arterial, cardiovascular, and cerebrovascular diseases." (PMID 36644256, 2022). "We found that increased CD34+CD133+ EPC frequency was significantly associated with decreased AD risk among those who had peripheral vascular diseases (HR = 0.62, 95% CI: 0.40–0.94, P = 0.02) or cerebrovascular disease (HR = 0.58, 95% CI: 0.35–0.96, P = 0.03)." (PMID 38854406, 2024). "Based on data from previous studies in cardio- and cerebrovascular diseases, demonstrating a direct interaction between mCRP and endothelial cells, we performed double immune stainings with mCRP and the specific endothelial marker CD34." (PMID 37006231, 2023). "CD34, as a powerful pan-endothelial cell marker, is widely expressed in mature vascular endothelial cells and has garnered extensive interest among clinicians in clinical practice, especially in the fields of cardiovascular and cerebrovascular diseases and cancer." (PMID 39906069, 2025).
cholangiocarcinoma (6 papers, 2013 to 2025). A carcinoma that arises from the intrahepatic biliary tree (intrahepatic cholangiocarcinoma) or from the junction, or adjacent to the junction, of the right and left hepatic ducts (hilar cholangiocarcinoma). "Based on the results of analysis on cholangiocarcinoma, cutoff points for high CD34 expression and high Ki-67 labeling index were defined as follows." (PMID 24131658, 2013). "Consequently, these images demonstrated that at the invasive margin in replacing HGP, Keratin 7-positive cholangiocarcinoma cells were closely opposed to CD34-positive sinusoid-like vessels (vessel co-option) in addition to TAGLN-positive tumoral vessels." (PMID 38960952, 2024). "Cholangiocarcinoma, metastasis, and HCC stain negative for CD31, CD34, and factor VIII, and HCC stains positive for cluster of differentiation-10 (CD10), arginase, and hepatocyte paraffin 1 (HepPar-1) with polyclonal carcinoembryonic antigen." (PMID 40225499, 2025).
chronic granulomatous disease (6 papers, 2014 to 2025). Chronic granulomatous disease (CGD) is a rare primary immunodeficiency, mainly affecting phagocytes, which is characterized by an increased susceptibility to severe and recurrent bacterial and fungal infections, along with the development of granulomas. "Previous studies have demonstrated that gene editing is feasible in CD34+ cells from patients with hematological disorders such as SCID‐X1 or chronic granulomatous disease (CGD)." (PMID 28899930, 2017).
cyst (6 papers, 2014 to 2025). A sac-like closed membranous structure that may be empty or contain fluid or amorphous material. "Of these lesions, only cystic hemolymphangioma is characterized by the presence of both D2-40-positive and CD34-positive endothelial-like cells lining the inner surface of the cyst, making it rarer than cystic lymphangioma." (PMID 40026945, 2025). "The CD34-positive vascular endothelium was abundant in the cyst wall, suggesting significant angiogenesis." (PMID 39516969, 2023). "The cyst wall had abundant CD34-positive vascular endothelium, suggestive of rapid enlargement due to the influx of exudate associated with angiogenesis." (PMID 39516969, 2023). "In the current case, the endothelium covering the large cavity of the cyst was D2-40 positive, while the capillary structures exhibited a mixture of D2-40-positive, bloodless vessels and CD34-positive, blood-filled capillaries, consistent with hemolymphangioma." (PMID 40026945, 2025). "The inner cyst lining and the endothelial-like cells of the small lumens of lymphatic capillaries tested positive for D2-40 immunostaining, while endothelial-like cells of capillary-like structures were positive for CD34." (PMID 40026945, 2025). "Immunohistochemical staining including factor VIII, podoplanin, endothelial markers (CD31, CD34, ERG avian V‐ets erythroblastosis virus E26 oncogene homolog), FLI1 (“friend leukemia factor”), and matrix metalloproteinase‐1 (MMP-1) can help to identify cAS in the cyst walls." (PMID 35543776, 2023).
desmoid fibromatosis (6 papers, 2014 to 2025). "In our case, histopathology and immunohistochemistry, showing nuclear β-catenin positivity and negativity for CD34, S100 protein, and SMA, established the definitive diagnosis of desmoid fibromatosis." (PMID 41226994, 2025). "Immunostaining showed negative results for c-kit, CD34, desmin, and S-100, while positive results for β-catenin confirmed the diagnosis of a desmoid tumor." (PMID 40124320, 2025). "Histology and immunohistochemistry analysis identified the tumor as a desmoid type fibromatosis (β catenin positive; S100, CD34, SMA negative)." (PMID 41226994, 2025). "GIST differs from desmoid-type fibromatosis in that it is stained for CD34 and CD117 stains, not usually expressed in desmoid-type fibromatosis." (PMID 25349618, 2014). "Pathological examination revealed atypical cells with spindle-shaped nuclei and collagen fiber hyperplasia in the stroma, and immunostaining was negative for c-kit, CD34, desmin, S-100, and positive for β-catenin, leading to a confirmed diagnosis of desmoid tumor." (PMID 40124320, 2025).
ductal carcinoma in situ (6 papers, 2002 to 2026). "However, the stroma surrounding ductal carcinoma in situ was also characterized by loss of CD34 fibrocytes." (PMID 23469238, 2013). "We already carried out a study on the stromal expression of CD34 and SMA in ductal carcinoma in situ (DCIS)." (PMID 25011545, 2014).
Fanconi anemia (6 papers, 2017 to 2025). Fanconi anemia (FA) is a hereditary DNA repair disorder characterized by progressive pancytopenia with bone marrow failure, variable congenital malformations and predisposition to develop hematological or solid tumors. "Following the clinical studies in Fanconi anemia in 2019, preclinical studies reported in May 2024 showed that lentivirus-mediated genetically edited CD34+ hematopoietic stem cells in Diamond–Blackfan anemia improved erythroid maturation." (PMID 39062641, 2024). "Preclinical studies toward treating Fanconi anemia have been performed using adenine base editors and sgRNA in patient-derived and healthy donor-derived lymphoblastoid cell lines and CD34+ hematopoietic stem cells from healthy donors and patients with Fanconi anemia." (PMID 39062641, 2024). "During the first year of clinical searches, we performed confirmatory testing for the best three resulting UCB units per patient and found a particular case in which all CD34+ cell viability data were below our acceptability criteria (aplastic/Fanconi anemia patient; AFA)." (PMID 31575081, 2019).